TRNP1 (TMF1 regulated nuclear protein 1)
Description:
DNA-binding factor that regulates the expression of a subset of genes and plays a key role in tangential, radial, and lateral expansion of the brain neocortex. Regulates neural stem cells proliferation and the production of intermediate neural progenitors and basal radial glial cells affecting the process of cerebral cortex gyrification. May control the proliferation rate of cells by regulating their progression through key cell-cycle transition points (By similarity).
Synonyms: C1orf225; TRNP; TNRP
Tractability: PROTAC: UniProt records ubiquitination sites on it.
Gene: Protein-coding gene on chromosome 1 (26,993,692 to 27,001,912, forward strand). Ensembl gene ENSG00000253368.
Subcellular location: Nucleus
Gene Ontology:
Molecular function: DNA binding
Biological process: cerebellar cortex morphogenesis; neural precursor cell proliferation; regulation of cell cycle; regulation of cell population proliferation
Cellular component: euchromatin; nucleus
Genetic constraint (gnomAD): Loss-of-function variants: 16 observed, 6.99 expected, observed/expected ratio (o/e) 2.29. That is too few expected variants to judge how well the gene tolerates losing a copy. Missense variants: 333 observed, 186.75 expected, observed/expected ratio (o/e) 1.78, 90% interval 1.63 to 1.94. Synonymous variants: 135 observed, 80.43 expected, observed/expected ratio (o/e) 1.68, 90% interval 1.46 to 1.91.
Homologues: Orthologues: chimpanzee TRNP1 (98% identical), macaque TRNP1 (96% identical), mouse Trnp1 (86% identical), pig TRNP1 (86% identical), dog TRNP1 (85% identical), rat Trnp1 (85% identical), zebrafish si:ch211-160f23.7 (23% identical).
Diseases named in the same sentence as TRNP1 in open-access papers:
TRNP1 is named in the same sentence as 3 diseases in open-access papers, as found by Europe PMC text mining. Sharing a sentence is not in itself a finding about the gene and the disease. The quoted sentences say what the papers report.
breast carcinoma (1 paper, 2023). "Similarly, overexpression of Trnp1 increases proliferation in vitro in NSCs or breast cancer cells." (PMID 36947129, 2023).
tumor (3 papers, 2020 to 2023). "GATA3, FOXA1, RASSF5, PTPN6, and TRNP1, involved in the luminal markers and negative regulation of cell proliferation, are related to tumor suppression and chemotherapy resistance." (PMID 36344487, 2022). "K-M curves showed that upregulated TRNP1, CCDC112, CFL1 were associated with poor OS) and CYB5D2, SLC22A1 were protective genes (expression of CYB5D2, SLC22A1 were decreased in tumor tissues, and higher expression of CYB5D2, SLC22A1 was associated with good OS)." (PMID 36881382, 2023).
cancer (2 papers, 2020). A tumor composed of atypical neoplastic, often pleomorphic cells that invade other tissues. "As Trnp1 is expressed in many stem cells of other organs during embryogenesis and various cancer cells, its novel role in co‐regulating nuclear MLOs and M‐phase progression may have a broader relevance beyond the developing nervous system." (PMID 32627867, 2020).